EHD1 (EH domain containing 1)
Diseases named in the same sentence as EHD1 in open-access papers (continued):
Sharing a sentence is not in itself a finding about the gene and the disease.
gastric cancer (1 paper, 2022). A primary or metastatic malignant neoplasm involving the stomach. "F nucleatum-induced neutrophil transcriptional activation may be implicated in gastric cancer via several candidate genes including DNAJB1, EHD1, IER2, CANX, and PH4B among the top genes of interest." (PMID 36033825, 2022). "F nucleatum-induced neutrophil transcriptional activation may be implicated in gastric cancer via several candidate genes including DNAJB1, EHD1, IER2, CANX, and PH4B." (PMID 36033825, 2022).
hearing loss (1 paper, 2023). "Recently, we described the first human disease caused by a mutation in EHD1: The homozygous p.R398W missense mutation of EHD1 resulted in tubular proteinuria and sensorineural hearing loss in affected patients." (PMID 37900275, 2023).
ichthyosis (1 paper, 2023). Disorders of cornification that are characterized by visible scaling and/or hyperkeratosis of most or all of the skin. "Diseases associated with EHD1 include plasmacytoid cystic tumor of the pancreas and cerebral hypoplasia, neuropathy, ichthyosis, and palmoplantar keratosis syndrome." (PMID 38169604, 2023).
malaria (1 paper, 2025). Malaria is a serious and sometimes fatal disease caused by a parasite that commonly infects a certain type of mosquito which feeds on humans. "Genes involved in ATP metabolism (EHD1), glycolysis (GYG1), and acetyl coenzyme A metabolism (NAT1) were also enriched in symptomatic and underrepresented in asymptomatic malaria." (PMID 40830592, 2025).
malignant mesothelioma (1 paper, 2020). A malignant neoplasm of the pleura or peritoneum, arising from mesothelial cells. "Using whole exome sequencing of five WDPMs of the peritoneum, we have identified distinct mutations in EHD1, ATM, FBXO10, SH2D2A, CDH5, MAGED1, and TP73 shared by WDPM cases but not reported in malignant mesotheliomas." (PMID 32545767, 2020). "Moreover, EHD1 has been associated with cell proliferation, apoptosis, metastasis, and drug resistance in breast and non-small cell lung cancer (NSCLC) but has not been reported to be abnormal in malignant mesotheliomas." (PMID 32545767, 2020).
malocclusion (1 paper, 2010). "In several cases, Ehd1-/- females displayed malocclusion (4/18, 22%) which required bi-weekly incisor trimming into adulthood to prevent death." (PMID 20359371, 2010).
metastatic tumors (1 paper, 2023). "In a large EWS tumor panel, we found moderate to high EHD1 overexpression in nearly 90% of patients, with significantly higher levels in metastatic tumors." (PMID 37474760, 2023).
muscular dystrophy (1 paper, 2015). Muscular dystrophy (MD) refers to a group of more than 30 genetic diseases characterized by progressive weakness and degeneration of the skeletal muscles that control movement. "To determine if Ehd1-heterozygous mice display signs of muscular dystrophy, due to the decreased levels of EHD1, we evaluated the muscle histopathology of both young and aged mice." (PMID 26325203, 2015). "Ehd1-heterozygous mice were found to have strikingly elevated serum creatine kinase and smaller myofibers, but did not display findings of muscular dystrophy." (PMID 26325203, 2015).
non-Hodgkin lymphoma (1 paper, 2007). Distinct from Hodgkin lymphoma both morphologically and biologically, non-Hodgkin lymphoma (NHL) is characterized by the absence of Reed-Sternberg cells, can occur at any age, and usually presents as a localized or generalized lymphadenopathy associated with fever and weight loss. "We observed that EHD1 upregulated in Non-Hodgkin Lymphoma (NHL) and in a few cases of RMS; while in a majority of RMS and EWS cases it is moderately expressed." (PMID 17207284, 2007).
osteosarcoma (1 paper, 2019). A usually aggressive malignant bone-forming mesenchymal neoplasm, predominantly affecting adolescents and young adults. "The prognosis for patients with low expression of EHD1 in osteosarcomas was significantly better than that for patients with high expression of EHD1 (log-rank test, P = 0.019)." (PMID 30975166, 2019). "The expression of EHD1 was negatively correlated with DFS and OS of osteosarcoma patients; therefore, the expression of EHD1 is a prognostic marker for prediction and prevention of osteosarcomas." (PMID 30975166, 2019). "The prognosis for patients with low expression of EHD1 in osteosarcomas was significantly better than those with high expression of EHD1." (PMID 30975166, 2019). "The prognosis for patients who had low expression of EHD1 in osteosarcomas was significantly better (log-rank test, P = 0.045) compared with patients who had high expression of EHD1." (PMID 30975166, 2019). "The median DFS time in patients who showed high expression of EHD1 was 46.8 months, and the prognosis for patients with low expression of EHD1 in osteosarcomas was significantly better than those with high expression of EHD1." (PMID 30975166, 2019). "The expression of EHD1 in tumor and normal tissues collected from 57 osteosarcoma patients was measured using immunohistochemistry techniques, and correlations with the clinicopathological features of patients were sought." (PMID 30975166, 2019). "Notwithstanding this study’s limitation, in that it had such a small sample size, the identification of the prognostic potential of EHD1 expression warrants further study in larger cohorts to validate the effects found in osteosarcoma patients." (PMID 30975166, 2019). "The present study aimed to investigate the usefulness of EHD1 as a prognostic marker for osteosarcoma." (PMID 30975166, 2019). "The prognosis for patients with low expression of EHD1 in osteosarcomas was significantly better than patients with high expression of EHD1." (PMID 30975166, 2019). "The prognosis for patients with low expression of EHD1 in osteosarcomas was significantly better (log-rank test, P = 0.019) compared with patients with high expression of EHD1." (PMID 30975166, 2019). "Analysis of the same set of patient data using a multivariate Cox proportional hazards model showed that tumor size (P = 0.008; HR, 5.854; 95% CI, 1.587–21.597) and EHD1 expression (P = 0.007; HR, 6.372; 95% CI, 1.645–24.676) were independent prognostic indicators of OS in osteosarcoma patients." (PMID 30975166, 2019). "Considering all of these observations, the expression of EHD1 could be considered as a prognostic marker for osteosarcoma prediction and prevention." (PMID 30975166, 2019). "In addition, tumor size and EHD1 expression were found to be independent prognostic indicators for osteosarcomas." (PMID 30975166, 2019). "Univariate Cox regression model analysis showed that age (P = 0.015; HR, 0.945; 95% CI, 0.903–0.989), tumor size (P = 0.042; HR, 3.155; 95% CI, 1.045–9.525), and EHD1 expression (P = 0.026; HR, 3.202; 95% CI, 1.149–8.92) were independent prognostic indicators of OS in osteosarcoma patients." (PMID 30975166, 2019). "EHD1 expression was found to be an independent prognostic indicator of OS in osteosarcoma patients." (PMID 30975166, 2019). "The expression of EHD1 was negatively correlated with DFS and OS of osteosarcoma patients, and thus, the expression of EHD1 could be considered as a prognostic marker for the prediction and prevention of osteosarcoma." (PMID 30975166, 2019). "The expression of EHD1 was negatively correlated with DFS and OS in osteosarcoma patients, and thus, the expression of EHD1 could be considered as a prognostic marker for osteosarcoma prediction and prevention." (PMID 30975166, 2019).
osteosarcoma (continued). "EHD1 expression [P = 0.020; HR, 5.582; 95% confidence intervals (CI), 1.314–23.72] was an independent prognostic indicator of DFS in osteosarcoma patients; tumor size and EHD1 expression of osteosarcomas were independent prognostic indicators of OS in osteosarcoma patients." (PMID 30975166, 2019). "Multivariate Cox proportional hazards model analysis of the same set of patient data showed that EHD1 expression (P = 0.020; HR, 5.582; 95% CI, 1.314–23.72) was independent of prognostic indicators for DFS in osteosarcoma patients." (PMID 30975166, 2019).
peritoneal mesothelioma (1 paper, 2020). A benign or malignant mesothelial neoplasm that arises from the peritoneum. "Notably, we found WDPM specific mutations in EHD1, FBXO10, CHD5, MAGED1, ATM, and TP73 genes that were absent in peritoneal mesothelioma." (PMID 32545767, 2020).
polycystic kidney disease (1 paper, 2026). A usually autosomal dominant and less frequently autosomal recessive genetic disorder characterized by the presence of numerous cysts in the kidneys leading to end-stage renal failure. "Although many disease links remain correlative or model-based, the recent identification of an EHD1 founder mutation causing proteinuria, hearing loss, and polycystic kidney disease provides direct genetic evidence connecting EHD dysfunction to human pathology." (PMID 42322139, 2026).
sarcoma (1 paper, 2023). A usually aggressive malignant neoplasm of the soft tissue or bone. "Here, using Ewing Sarcoma (EWS) as a tumor model, we demonstrate that the intracellular vesicular traffic regulatory protein EHD1 promotes tumorigenesis and metastasis by serving as a required element of IGF-1R traffic to enable IGF-1R-mediated oncogenic programs." (PMID 37474760, 2023).
tumor of the colon (1 paper, 2007). "Although EHD1 has not been studied in the context of cancer biology, it seems to be highly expressed in metastatic colon cancer than in tumor of the colon as per the GEO profiles (GEO: GPL96 208112)." (PMID 17207284, 2007).
tumor (16 papers, 2007 to 2024). "The variant allele frequency (VAF) of EHD1 was in the range 29–43%, indicating its likely clonal origin (given that the tumor cellularity of the WDPM tissues were estimated to be about 50%)." (PMID 32545767, 2020). "The microarray analysis revealed that EHD1 was significantly correlated with tumor angiogenesis, and loss- and gain-of-function experiments demonstrated that EHD1 potentiates HUVEC proliferation, migration and tube formation." (PMID 31023336, 2019). "To understand the underlying mechanisms and identify the pathways driven by EHD1 in tumor angiogenesis, we analyzed microarray data using classical pathway enrichment analysis." (PMID 31023336, 2019). "Our IHC results suggested that EHD1 expression might be positively associated with tumour metastasis." (PMID 35485206, 2022). "Overall, these findings indicate that EHD1 is a tumour resistance-associated protein." (PMID 27411790, 2016). "In conclusion, our analyses in an EWS tumor model show that EHD1 overexpression promotes oncogenesis by post-translationally upregulating the trafficking itinerary of an RTK, IGF-1R." (PMID 37474760, 2023). "To identify EWS cell models suitable for delineating the role of EHD1 in tumor biology, we first queried the Cancer Cell Line Encyclopedia (CCLE)/DepMap mRNA expression database." (PMID 37474760, 2023). "It is possible that the role of EHD1 in tumor progression is related to its role in tumor angiogenesis." (PMID 35512017, 2022). "Downregulation of Eps15 homology domain 1 (EHD1) attenuated glycolysis and tumor growth in A549 cells, NCI-H1299 cells, and a xenograft mouse model." (PMID 36532721, 2022). "Taken together, these data demonstrate that EHD1 plays an important role in promoting angiogenesis and tumor growth." (PMID 31023336, 2019). "Correlation of EHD1 expression with the clinicopathological features of patients, including age, gender, tumor histology, tumor size, and AJCC stage in SCLC patients was assessed." (PMID 30975166, 2019). "Consistent with our observations in tumor cell lines and xenograft models, the distribution and intensity of EHD1 were positively correlated with β2AR, VEGFA and CD31 in NSCLC tissue specimens." (PMID 31023336, 2019). "Our current study showed that EHD1 potentiates angiogenesis and tumor growth via the β2AR signaling pathway." (PMID 31023336, 2019). "We and other researchers have reported that EHD1 plays a significant tumor-promoting role as an oncogene in various cancers." (PMID 31023336, 2019). "High expression of EHD1 in tumor tissues was positively correlated only with the disease type (P = 0.025)." (PMID 30975166, 2019). "The knockdown of EHD1 inhibited the β-adrenergic signaling pathway, which is involved in tumor angiogenesis and VEGFA regulation." (PMID 31023336, 2019). "The proangiogenic role of EHD1 was confirmed in xenograft tumor models, and immunohistochemistry (IHC) analysis confirmed that EHD1 expression was positively correlated with VEGFA expression, microvessel density (MVD) and β2AR expression in patient specimens." (PMID 31023336, 2019). "In the present study, we provide the first demonstration that EHD1 potentiates tumor angiogenesis in vitro and in vivo." (PMID 31023336, 2019). "Relative to the those implanted with the control cells, the mice implanted with EHD1-knockdown cells showed significantly less tumor growth and a decreased tumor weight." (PMID 31023336, 2019). "A549 cells stably transfected with EHD1-Ctrl (Ctrl), EHD1-shRNA (Sh), EHD1-shRNA/Ctrl (Sh/Ctrl) and EHD1-shRNA/R (Sh/R) were subcutaneously injected into the alar skin of the mice, and the tumor growth over 7 and 28 days after implantation was monitored." (PMID 31023336, 2019). "Luciferin-based bioluminescence imaging at 7 and 28 days revealed that the knockdown of EHD1 significantly decreased the tumor development potential of A549 cells." (PMID 31023336, 2019).
tumor (continued). "We next examined EHD1 protein expression in fresh tumor and normal tissues by western blot analysis." (PMID 27531895, 2017). "IHC analysis revealed that expression of EHD1 protein was significantly higher in tumor tissues than in adjacent normal lung tissues." (PMID 27531895, 2017). "The results showed that tumor tissues expressed ~6.2-fold more EHD1 mRNA than normal tissues (P<0.001)." (PMID 27531895, 2017). "Expression of EHD1 mRNA was then examined in tumor and normal tissues using real-time quantitative RT-PCR." (PMID 27531895, 2017). "The main purpose of this study was to examine a possible function of EHD1 in tumor cell metastasis in vitro and in vivo." (PMID 27531895, 2017). "We conclude that EHD1 is required for tumour growth and that it is a regulator of CDDP accumulation and cytotoxicity." (PMID 27411790, 2016). "These cell biological findings raise the possibility that overexpression of EHD1 in tumors could promote RTK-dependent oncogenic signaling by enabling the cell surface display of RTKs on tumor cells." (PMID 37474760, 2023). "EHD1 promoted tumor progression through the activation of 14-3-3ζ/β-catenin/c-Myc signaling." (PMID 36532721, 2022). "To examine whether Hippo signalling activity affects tumour metastasis promoted by EHD1, we treated nude mice with VP or DMSO on day 10 after intravenous injection with EHD1KD+WT." (PMID 35485206, 2022). "Xenograft tumor models were used to investigate the role of EHD1 in NSCLC tumor growth." (PMID 31023336, 2019). "Aberrant VEGFA or β2AR expression significantly affected EHD1-mediated tumor angiogenesis." (PMID 31023336, 2019). "Here, we propose a working model of EHD1 function in tumor angiogenesis." (PMID 31023336, 2019). "Mammalian Eps15 homology domain 1 (EHD1) plays a promotive role in tumor progression, but its role in cancer angiogenesis remains unknown." (PMID 31023336, 2019). "EHD1 protein expression was a positive expression in examined tumor tissues." (PMID 30975166, 2019). "Based on our microarray analysis result, we speculated EHD1 could act as a regulator of the EMT process in tumor cells." (PMID 27531895, 2017). "The selective knockdown of EHD1 in tumours offers a strategy for enhancing the efficacy of CDDP." (PMID 27411790, 2016). "Over the past five years, we have revealed that EHD1 overexpression in NSCLC predicts poor prognosis for patients and that EHD1 might play a pivotal role in tumor metastasis, stemness, chemotherapy resistance and epidermal growth factor receptor (EGFR)-tyrosine kinase inhibitor (TKI) resistance." (PMID 31023336, 2019). "Moreover, we revealed that EHD1 promoted angiogenesis and tumor growth in a VEGFA-dependent manner." (PMID 31023336, 2019). "The in vivo results were consistent with the observations in vitro: tumours treated with the miR-590 agomir were more sensitive to erlotinib treatment than the miR-NC agomir-treated tumours (704.70 ± 32.99 mm3 vs. 348.70 ± 53.72 mm3, P < 0.05) because EHD1 expression was low." (PMID 29549343, 2018). "Western blotting of resected tumor lysates confirmed the Dox-induced EHD1 KD in the shEHD1 group, and IHC staining with anti-human CD99 confirmed the tumor mass." (PMID 37474760, 2023). "We detected the expression of EHD1, β2AR and VEGFA in freshly frozen xenograft tumor tissue by Western blot and found that the EHD1 levels were positively correlated with β2AR and VEGFA expression." (PMID 31023336, 2019). "The Sh/R-apatinib mice showed a decreased tumor volume and a lower tumor weight than the control mice, which suggested that VEGFA inhibition impaired the EHD1-induced effect on tumor growth." (PMID 31023336, 2019). "However, the involvement of EHD1 in tumor angiogenesis is unknown." (PMID 31023336, 2019). "In this study, we examined the effect of EHD1 on tumor angiogenesis in NSCLC and found that EHD1 induces NSCLC angiogenesis by upregulating VEGFA expression." (PMID 31023336, 2019).
tumor (continued). "Expressions of the remaining three genes (NAB2, EHD1 and LSP1) are either upregulated or downregulated in the various tumors and also in SRBCTs depending on the tumor subgroups." (PMID 17207284, 2007). "To assess the impact of inducible EHD1 KD on pre-formed tumors, we implanted Nude mice with shNTC or shEHD1 (#3) TC71 cell lines carrying the TdTomato-luciferase reporter, and monitored the tumor growth by IVIS imaging, as above." (PMID 37474760, 2023). "To assess if EHD1 is overexpressed in EWS patient tumors and if its overexpression bears any relationship with patient survival, we queried the publicly-available EWS patient tumor mRNA expression data using the R2 Genomics Analysis and Visualization Platform." (PMID 37474760, 2023). "Thus, EHD1 overexpression leads to persistent β2AR signaling activity, and upregulated VEGFA stimulates tumor angiogenesis." (PMID 31023336, 2019). "In addition, we investigated the impact of β2AR signaling on EHD1-induced NSCLC angiogenesis and tumor growth in vivo." (PMID 31023336, 2019). "To investigate whether these effects can regulate CSC properties in vivo, we examined the expression of EHD1 and CD133 in the developed tumours." (PMID 29549343, 2018). "We favour the interpretation that platinum-based chemotherapy is more effective against EHD1-negative tumours." (PMID 27411790, 2016). "The tumor center was characterized by a higher abundance of transferrin (TF), endoplasmic reticulum oxidoreductase 1 (ERO1)-like protein (ERO1A), EH domain-containing protein 1 (EHD1), keratin 5 (KRT5), serpin H1 protein (SERPINH1), and lactate dehydrogenase A (LDHA)." (PMID 35512017, 2022).